TTC5 (tetratricopeptide repeat domain 5)
Description:
Cofactor involved in the regulation of various cellular mechanisms such as actin regulation, autophagy, chromatin regulation and DNA repair. In non-stress conditions, interacts with cofactor JMY in the cytoplasm which prevents JMY's actin nucleation activity and ability to activate the Arp2/3 complex. Acts as a negative regulator of nutrient stress-induced autophagy by preventing JMY's interaction with MAP1LC3B, thereby preventing autophagosome formation (By similarity). Involves in tubulin autoregulation by promoting its degradation in response to excess soluble tubulin. To do so, associates with the active ribosome near the ribosome exit tunnel and with nascent tubulin polypeptides early during their translation, triggering tubulin mRNA-targeted degradation. Following DNA damage, phosphorylated by DNA damage responsive protein kinases ATM and CHEK2, leading to its nuclear accumulation and stability. Upon heat-shock stress, forms a chromatin-associated complex with heat-shock factor 1 HSF1 and p300/EP300 to stimulate heat-shock-responsive transcription, thereby increasing cell survival. Mitochondrial TTC5/STRAP interacts with ATP synthase subunit beta ATP5F1B which decreased ATP synthase activity and lowers mitochondrial ATP production, thereby regulating cellular respiration and mitochondrial-dependent apoptosis.
Synonyms: Strap; NEDCAFD
Tractability: Small molecule: it has a binding pocket of medium quality. PROTAC: ubiquitination databases record sites on it; its protein half-life has been measured.
Gene: Protein-coding gene on chromosome 14 (20,256,558 to 20,305,963, reverse strand). Ensembl gene ENSG00000136319.
Subcellular location: Nucleus; Cytoplasm; Cytoplasmic vesicle; Mitochondrion matrix
Subcellular location (Human Protein Atlas): Nucleoplasm
Gene Ontology:
Molecular function: protein binding; ribosome binding; chromatin binding; DNA binding
Biological process: positive regulation of mRNA catabolic process; cellular response to starvation; DNA damage response; positive regulation of RNA metabolic process; regulation of gene expression
Cellular component: cytoplasm; cytosol; nucleoplasm; cytoplasmic vesicle; mitochondrial matrix; mitochondrion; nucleus
Genetic constraint (gnomAD): Loss-of-function variants: 40 observed, 50.35 expected, observed/expected ratio (o/e) 0.79, 90% interval 0.62 to 1.03. The upper end of that interval is the gene's LOEUF score, 1.03, which puts it in group 4 of 6, group 1 being the genes least tolerant of losing a copy. Missense variants: 467 observed, 496.81 expected, observed/expected ratio (o/e) 0.94, 90% interval 0.87 to 1.01. Synonymous variants: 178 observed, 193.62 expected, observed/expected ratio (o/e) 0.92, 90% interval 0.81 to 1.04.
Homologues: Orthologues: chimpanzee TTC5 (99% identical), macaque TTC5 (99% identical), pig TTC5 (93% identical), rabbit TTC5 (93% identical), mouse Ttc5 (90% identical), rat Ttc5 (90% identical), guinea pig TTC5 (90% identical), dog TTC5 (90% identical), tropical clawed frog ttc5 (65% identical), zebrafish ttc5 (59% identical), Caenorhabditis elegans Y37E3.1 (23% identical).
Diseases named in the same sentence as TTC5 in open-access papers:
TTC5 is named in the same sentence as 12 diseases in open-access papers, as found by Europe PMC text mining. Sharing a sentence is not in itself a finding about the gene and the disease. The quoted sentences say what the papers report.
acute myeloid leukemia (1 paper, 2025). Acute myeloid leukemia (AML) is a group of neoplasms arising from precursor cells committed to the myeloid cell-line differentiation. "Moreover, TTC5 is a MYC interactor in acute myeloid leukemia stem cells, preventing excessive accumulation of MYC." (PMID 41211440, 2025).
cardiac hypertrophy (1 paper, 2024). "PARP2 has been associated with cardiac hypertrophy, TEP1 has been associated with myocardial infarction (MI) and ischemic stroke, and TTC5 has been associated with cardiovascular disease." (PMID 38473795, 2024).
ischemia (1 paper, 2024). A hypoperfusion of the BLOOD through an organ or tissue caused by a PATHOLOGIC CONSTRICTION or obstruction of its BLOOD VESSELS, or an absence of BLOOD CIRCULATION. "Regarding the TTC5 gene, tetratricopeptide repeat domain 5, a previous study has described that inhibiting TTC5 expression leads to a significant attenuation of the damage suffered by cardiomyocytes due to oxygen and glucose deprivation, such as in ischemia." (PMID 38473795, 2024).
lung carcinoma (1 paper, 2021).
thyroid cancer (1 paper, 2025).
tubulinopathies (1 paper, 2023). "These phenotypes overlap partially with both TTC5-linked disease and tubulinopathies, providing insights into the tissues and biological processes most reliant on tubulin autoregulation." (PMID 37295431, 2023).
cancer (2 papers, 2021 to 2025). A tumor composed of atypical neoplastic, often pleomorphic cells that invade other tissues. "The results here show a significant and complex association of TTC5 protein expression with the grade, stage of cancer, and OS." (PMID 34947995, 2021). "Several reports suggest that TTC5 controls elements of cytoskeleton actin and tubulin, which are crucial components of migratory and metastatic potential of cancer cells potentially explaining association with metastatic and node status." (PMID 34947995, 2021). "Significant associations were observed between the TTC5 protein and cancer grade (p = 0.039), although it is difficult to conclude what type of association this represents, given different trends for single and double grades." (PMID 34947995, 2021). "Taken together, our study demonstrates that the CARM1-PI3KC2α axis is a key regulator of TTC5-mediated tubulin autoregulation and that disrupting this axis enhances the anti-cancer activity of MTAs." (PMID 40045375, 2025). "The incidence of TTC5 expression indicated that 183 cases positively stained for TTC5, mostly found in the cytoplasm of the cancer cells." (PMID 34947995, 2021).
tumour (1 paper, 2021). "The TTC5 protein levels were significantly associated with the grade, tumor size, and node involvement in a complex manner." (PMID 34947995, 2021). "TTC5 seems to be positively associated with tumor size and node involvement, whereas a potential association with metastasis is difficult to interpret due a difference in number of samples analysed in different categories." (PMID 34947995, 2021). "It seems that TTC5 is positively associated with higher tumour stage (T2 versus T1) and nodes involvement (N1 versus N0), whereas association with distant metastasis (M status) is inconclusive due to lack of a representative sample, highlighting the need for a larger sample analysis." (PMID 34947995, 2021).
TTC5 also shares sentences with these, for which no sentence is quoted: cardiovascular disease (1 paper); ischemic stroke (1); myocardial infarction (1); osteosarcoma (1).